CSNK1D (casein kinase 1 delta)
Description:
Essential serine/threonine-protein kinase that regulates diverse cellular growth and survival processes including Wnt signaling, DNA repair and circadian rhythms. It can phosphorylate a large number of proteins. Casein kinases are operationally defined by their preferential utilization of acidic proteins such as caseins as substrates. Central component of the circadian clock. In balance with PP1, determines the circadian period length through the regulation of the speed and rhythmicity of PER1 and PER2 phosphorylation. Controls PER1 and PER2 nuclear transport and degradation. YAP1 phosphorylation promotes its SCF(beta-TRCP) E3 ubiquitin ligase-mediated ubiquitination and subsequent degradation. DNMT1 phosphorylation reduces its DNA-binding activity. Phosphorylation of ESR1 and AIB1/NCOA3 stimulates their activity and coactivation. Phosphorylation of DVL2 and DVL3 regulates WNT3A signaling pathway that controls neurite outgrowth. Phosphorylates NEDD9/HEF1 (By similarity). EIF6 phosphorylation promotes its nuclear export. Triggers down-regulation of dopamine receptors in the forebrain. Activates DCK in vitro by phosphorylation. TOP2A phosphorylation favors DNA cleavable complex formation. May regulate the formation of the mitotic spindle apparatus in extravillous trophoblast. Modulates connexin-43/GJA1 gap junction assembly by phosphorylation. Probably involved in lymphocyte physiology. Regulates fast synaptic transmission mediated by glutamate.
Synonyms: CKI-delta; CKId; HCKID; CKIdelta; ASPS; FASPS2
Tractability: Small molecule: a structure with a bound ligand is known; a high-quality ligand is known; it belongs to a druggable protein family. Antibody: its Gene Ontology location is reachable by antibodies, with high confidence; UniProt places it where antibodies can reach, with medium confidence; the Human Protein Atlas places it where antibodies can reach. PROTAC: it is named in the literature on targeted protein degradation; ubiquitination databases record sites on it; its protein half-life has been measured; a small molecule that binds it is known.
Target class: CK1 protein kinase group; Enzyme; CK1 protein kinase CK1 family; Protein Kinase; Kinase
Chemical probes: JNJ-78386204 (high quality), MU1742 (high quality)
Gene: Protein-coding gene on chromosome 17 (82,239,023 to 82,273,700, reverse strand). Ensembl gene ENSG00000141551.
Subcellular location: Cytoplasm; Nucleus; Cytoplasm, cytoskeleton, microtubule organizing center, centrosome; Cytoplasm, perinuclear region; Cell membrane; Cytoplasm, cytoskeleton, spindle; Golgi apparatus
Subcellular location (Human Protein Atlas): Cytosol; Plasma membrane; Actin filaments; End piece; Primary cilium; Principal piece
Pathways (Reactome):
Cell Cycle: AURKA Activation by TPX2; Loss of Nlp from mitotic centrosomes; Loss of proteins required for interphase microtubule organization from the centrosome; Recruitment of NuMA to mitotic centrosomes; Recruitment of mitotic centrosome proteins and complexes; Regulation of PLK1 Activity at G2/M Transition
Circadian clock: Phosphorylation and nuclear translocation of the CRY:PER:kinase complex; The CRY:PER:kinase complex represses transactivation by the BMAL:CLOCK (ARNTL:CLOCK) complex
Metabolism of RNA: Major pathway of rRNA processing in the nucleolus and cytosol
Organelle biogenesis and maintenance: Anchoring of the basal body to the plasma membrane
Vesicle-mediated transport: COPII-mediated vesicle transport
Gene Ontology:
Molecular function: cadherin binding; protein binding; protein kinase activity; protein serine kinase activity; protein serine/threonine kinase activity; tau-protein kinase activity; ATP binding
Biological process: Golgi organization; microtubule nucleation; non-motile cilium assembly; positive regulation of canonical Wnt signaling pathway; protein localization to centrosome; protein localization to cilium; protein localization to Golgi apparatus; protein phosphorylation; spindle assembly; circadian regulation of gene expression; COPII vesicle coating; endocytosis; midbrain dopaminergic neuron differentiation; positive regulation of non-canonical Wnt signaling pathway; positive regulation of proteasomal ubiquitin-dependent protein catabolic process; regulation of circadian rhythm; regulation of Wnt signaling pathway
Cellular component: centrosome; ciliary basal body; cytosol; Golgi apparatus; perinuclear region of cytoplasm; plasma membrane; spindle; spindle microtubule; endoplasmic reticulum-Golgi intermediate compartment membrane; nucleoplasm; nucleus; cytoplasm
Genetic constraint (gnomAD): Loss-of-function variants: 15 observed, 45.08 expected, observed/expected ratio (o/e) 0.33, 90% interval 0.22 to 0.51. The synonymous counts are far from expectation, so gnomAD's model fits this gene poorly and the ratio says little. Missense variants: 396 observed, 569.84 expected, observed/expected ratio (o/e) 0.69, 90% interval 0.64 to 0.75. Synonymous variants: 276 observed, 225.5 expected, observed/expected ratio (o/e) 1.22, 90% interval 1.11 to 1.35.
Homologues: Orthologues: guinea pig CSNK1D (99% identical), chimpanzee CSNK1D (98% identical), macaque CSNK1D (98% identical), pig CSNK1D (98% identical), mouse Csnk1d (97% identical), dog CSNK1D (97% identical), rat Csnk1d (97% identical), rabbit CSNK1D (95% identical), zebrafish csnk1db (91% identical), zebrafish csnk1da (89% identical), tropical clawed frog csnk1d (85% identical), Drosophila melanogaster dco (67% identical), and 1 more. Paralogues in human: CSNK1E (84% identical), CSNK1A1 (57% identical), CSNK1A1L (54% identical), CSNK1G3 (49% identical), CSNK1G1 (46% identical), CSNK1G2 (45% identical), TTBK1 (36% identical), TTBK2 (33% identical), VRK2 (25% identical), VRK1 (24% identical), CDC7 (21% identical), VRK3 (17% identical).
Diseases named in the same sentence as CSNK1D in open-access papers:
CSNK1D is named in the same sentence as 53 diseases in open-access papers, as found by Europe PMC text mining. Sharing a sentence is not in itself a finding about the gene and the disease. The quoted sentences say what the papers report.
breast carcinoma (8 papers, 2010 to 2025). "This study provides evidences that the kinase CSNK1D is implicated in breast cancer cell growth, migration, invasion and metastasis." (PMID 30112110, 2018). "The Casein kinase 1 delta (CSNK1D) has been implicated in colon, pancreatic and breast cancer and reduced CSNK1D activity impairs mammary tumorigenesis in vivo." (PMID 25416589, 2014). "CSNK1D is associated with metastasis and relapse of breast cancer, and is overexpressed in lymph node positive breast cancer." (PMID 20409316, 2010). "Previous studies demonstrated the oncogenic role of CSNK1D in various cancers, including breast carcinoma, hepatocellular carcinoma, prostate cancer, glioblastoma, multiple myeloma, and bladder cancer." (PMID 41353440, 2025). "Keeping that motility is essential for cancer cell metastasis, we investigated if CSNK1D contributes to the metastatic potential of breast cancer cells." (PMID 30112110, 2018). "In this study, we provide evidences that CSNK1D plays a role in breast cancer cell migration and metastasis." (PMID 30112110, 2018). "To explore the relevance of CSNK1D expression in breast cancer, we analyzed CSNK1D expression in primary tumors and matched node metastasis." (PMID 30112110, 2018). "Together, these findings highlight an important role for CSNK1D in metastasis of breast cancer and provide evidences that CSNK1D inactivation specifically prevents metastasis of cancer cells." (PMID 30112110, 2018). "Aberrant expression of CSNK1D is described in several cancer types including breast cancer, where it is amplified in about 30% of triple negative breast (TNBC)." (PMID 30112110, 2018). "While previous studies have determined that CSNK1D plays a role in breast cancer cell proliferation, its role in cell migration, invasion and metastasis has not been investigated." (PMID 30112110, 2018). "Our results confirmed that the CSNK1D protein is highly expressed in primary breast tumors and matched metastatic lymph nodes and further support a potential role for CSNK1D in breast cancer metastasis." (PMID 30112110, 2018). "To further examine the effect of CSNK1D on the invasive potential of breast cancer cell line, we analyzed the invasion of MDA-MB-231 through a matrigel-coated Transwell filters." (PMID 30112110, 2018). "Altogether, our results indicate that the downregulation of CSNK1D expression inhibits the proliferation and reduces the migration and the metastasis of breast cancer cells." (PMID 30112110, 2018). "We show that CSNK1D knock-down by shRNA in MDA-MB-231 breast cancer cells significantly inhibit cell migration and invasion." (PMID 30112110, 2018). "Moreover, significantly elevated CSNK1D levels have been observed in various cancer types, including breast carcinoma, hepatocellular carcinoma, prostate cancer, glioblastoma, multiple myeloma, and bladder cancer." (PMID 41353440, 2025). "Existing research reported CSNK1D as a therapeutic target for breast cancer and bladder cancer." (PMID 41353440, 2025). "Finally, we show that CSNK1D knock-down significantly reduces tumor growth and lung metastasis of human breast cancer cells in xenograft model." (PMID 30112110, 2018). "We previously reported that CSNK1D, localized in the 17q25.3 genomic region, is frequently amplified in triple negative breast cancer, particularly in BRCA1 mutated breast cancer, and the increased copy number correlates with increased CSNK1D mRNA." (PMID 30112110, 2018). "The role of CSNK1D overexpression in breast cancer remained poorly investigated until recently." (PMID 30112110, 2018). "Since cells with altered expression of CSNK1D also have a reduced migration and invasion, we tested whether this could also affect the metastatic capacity of breast cancer cells in addition to the effect on primary tumor growth." (PMID 30112110, 2018). "Finally, we show that depletion of CSNK1D suppresses growth of human breast cancer xenografts and inhibits their metastatic potential in vivo." (PMID 30112110, 2018).
breast carcinoma (continued). "In conclusion, our results suggest that CSNK1D might influence the progression of breast cancer and metastasis via the regulation of tight junction proteins expression and might represent a potential therapeutic target in breast cancer." (PMID 30112110, 2018). "We show that the depletion of CSNK1D using shRNA mediated knock-down or pharmaceutical inhibition of CSNK1D significantly reduces the migration and invasion of MDA-MB-231 breast cancer cells in vitro." (PMID 30112110, 2018). "Interestingly, suppression of CSNK1D, which is highly homologous to and has overlapping function with CSNK1E, did not affect proliferation of β-catenin positive cancer cell lines, suggesting a specific role for CSNK1E, at least in the context of these breast cancer cells." (PMID 20126544, 2010).
Familial advanced sleep-phase syndrome (8 papers, 2010 to 2022). "Serine to glycine mutation in PER2 and mutation in casein kinase Iδ gene (CSNK1D) develop familial advanced sleep phase syndrome (FASPS) whereas point mutation in PRNP causes fatal familial insomnia (FFI)." (PMID 29607311, 2018). "The deregulation of CSNK1D expression or function has been observed in cancer, but also in several other pathologies like Alzheimer's disease or familial advanced sleep phase syndrome." (PMID 30112110, 2018). "Also in patients with non-small vessel disease familial advanced sleep phase syndrome (FASPS), which is caused by specific missense mutations in the CSNK1D gene, migraine with aura is prevalent." (PMID 32503413, 2020). "Genes with vascular and/or glial cell function emerged from investigating syndromes in which migraine is prevalent, such as NOTCH3 in cerebral autosomal dominant arteriopathy with subcortical infarcts and leukoencephalopathy (CADASIL) and CSNK1D in familial advanced sleep phase syndrome (FASPS)." (PMID 30634909, 2019).
migraine (8 papers, 2018 to 2024). "CSNK1D is a notable exception to the ion channel and glutamatergic-related genes implicated in the majority of monogenic migraine, and the connection between migraine and FASPs is consistent with a likely role of the hypothalamus in regulating physiological stresses and migraine susceptibility." (PMID 31226929, 2019). "Involved in migraine pathogenesis, the CSNK1D gene provides evidence for the involvement of the hypothalamus in the development of and susceptibility to migraine." (PMID 38731230, 2024). "In addition, in a transgenic mouse model of familial migraine, animals expressing a human migraine gene (casein kinase 1 delta) showed an even greater sensitivity to NTG-evoked hyperalgesia." (PMID 30618656, 2018).
hepatocellular carcinoma (7 papers, 2017 to 2025). A malignant tumor that arises from hepatocytes. "Based on previous research, it was discovered that overexpression of CSNK1D is linked to poor survival in hepatocellular carcinoma (HCC) patients." (PMID 37688771, 2023). "In total, 563 circadian genes were differently expressed in hepatocellular carcinoma; three of them—CSNK1D, CSNK1E and NPAS2—had a high correlation with the overall survival rate in LIHC patients." (PMID 37240761, 2023). "In vitro studies have revealed that CSNK1D serves as an oncogenic factor in hepatocellular carcinoma, highlighting its promising candidacy as a therapeutic target in the realm of cancer treatment." (PMID 37688771, 2023). "To further understand this relationship, we examined the expression of CSNK1D in hepatocellular carcinoma patients at different clinical stages." (PMID 37688771, 2023). "In vitro experiments have demonstrated the oncogenic role of CSNK1D in hepatocellular carcinoma, indicating its potential as a therapeutic target in cancer treatment." (PMID 37688771, 2023). "To evaluate the prognostic effect of CSNK1D, we conducted univariate and multivariate COX regression analyses, which revealed that CSNK1D is an independent prognostic factor for hepatocellular carcinoma." (PMID 37688771, 2023). "Our results demonstrate that CSNK1D has a good prognostic evaluation effect in hepatocellular carcinoma, with an AUC of 0.719, 0.624, and 0.618 for 1-year, 3-year, and 5-year survival rates, respectively." (PMID 37688771, 2023). "This study aimed to investigate the role of CSNK1D in multiple human cancers, particularly hepatocellular carcinoma (HCC), through in vitro experiments." (PMID 37688771, 2023). "The previous research findings have suggested that CSNK1D may have a significant role in the development of hepatocellular carcinoma." (PMID 37688771, 2023). "Taken together, our findings suggest that CSNK1D expression levels may serve as a valuable prognostic biomarker for hepatocellular carcinoma patients." (PMID 37688771, 2023). "To provide further confirm the prognostic value of CSNK1D in hepatocellular carcinoma (HCC), we analyzed the expression of CSNK1D in both cancerous and adjacent tissues from the ICGC-LIRI-JP cohort." (PMID 37688771, 2023). "CSNK1D expression was higher in hepatocellular carcinoma (HCC) with distant metastasis than in HCC without metastasis." (PMID 35880088, 2022).
advanced sleep phase syndrome (4 papers, 2014 to 2020). A very rare circadian rhythm sleep disorder characterized by very early sleep onset and offset possibly resulting in emotional and physical disruptions. "In addition, mutations in PER2 have been linked with advanced sleep phase syndrome, while mutations in CSNK1D and CRY1 have been linked to delayed sleep phase syndrome." (PMID 29230328, 2017). "Mutations in the CKIδ gene, CSNK1D, were found to cause familial advanced sleep phase syndrome (FASPS) in two large independent pedigrees." (PMID 31226929, 2019).
liver cancer (4 papers, 2021 to 2023). An epithelial or non-epithelial malignant neoplasm that arises from the liver. "Our findings suggest that abnormal expression of CSNK1D is closely linked to the prognosis of liver cancer patients." (PMID 37688771, 2023). "Furthermore, we delved into the consequential meaning of CSNK1D mutations by examining a liver cancer cell line." (PMID 37688771, 2023). "Subsequently, GSEA indicated that CSNK1D was implicated in a variety of HCC phenotypes, including cell cycle, epithelial-mesenchymal transition (EMT), liver cancer stem cell (CSC), liver cancer metastasis and HCC progenitor." (PMID 36460966, 2022). "Furthermore, the prognostic evaluation effect of CSNK1D was assessed using the ROC liver cancer overall survival rate." (PMID 37688771, 2023). "RT-PCR was employed to evaluate CSNK1D expression in normal liver and liver cancer cell lines." (PMID 37688771, 2023). "Furthermore, to strengthen the evidence regarding the prognostic implications of CSNK1D expression in liver cancer, we conducted an analysis using the liver cancer dataset GSE14520 obtained from the GEO database." (PMID 37688771, 2023). "Therefore, we further analyzed the relationship between CSNK1D expression and clinical pathological staging, and developed a nomogram to facilitate the use of CSNK1D in evaluating liver cancer prognosis." (PMID 37688771, 2023). "Additionally, in the liver cancer cell experiment, similar results were obtained, in which the CSNK1D, CSNK1E, and NPAS2 mRNA expression levels were strongly upregulated compared with those in normal liver cells." (PMID 34149816, 2021). "Next, we analyzed the expression levels of ACTG1, CSNK1D, PPP1CC, and BIRC5 in HCC tissue samples in normal liver (n = 160) and liver cancer (n = 369) samples from the GEPIA dataset." (PMID 33816607, 2021). "To explore the expression levels of genes (CSNK1D, CSNK1E, and NPAS2) in liver cancer, we compared the mRNA expression levels of tumor and normal tissues." (PMID 34149816, 2021). "We found that higher expression levels of CSNK1D, CSNK1E, and NPAS2 were significantly related to shorter OS of liver cancer patients." (PMID 34149816, 2021).
ovarian carcinoma (4 papers, 2012 to 2022). A malignant neoplasm originating from the surface ovarian epithelium. "For example, in ovarian cancer, CK1δ gene (CSNK1D) is amplified in about 4% of the cases reported and is much more rarely deleted, while point mutations are not recorded." (PMID 31799185, 2019). "Casein kinase 1 delta (CK1δ) has a tumor-promoting role in different cancers and it is genetically amplified in a portion of human epithelial ovarian cancer (EOC)." (PMID 31799185, 2019). "We further evaluated the correlations between PER1 and these 10 interacting proteins based on the GEPIA database and found that the expression of PER1 in ovarian cancer was correlated with that of ARNTL, CLOCK, CRY1, CRY2, CSNK1D, CSNK1E, NPAS2, and PER3." (PMID 34220965, 2021). "As presented by the forest plot, we observed that higher levels of CSNK1D were correlated to shorter DFS time in CHOL (cholangiocarcinoma), COAD (colon cancer), LIHC, and PRAD (prostate cancer); however, higher expression of CSNK1D was correlated to longer DFS time in BRCA and OV (ovarian cancer)." (PMID 35880088, 2022).
prostate carcinoma (3 papers, 2011 to 2025). A carcinoma that arises from epithelial cells of the prostate gland. "In prostate cancer, 9 CCGs, including CSNK1D, were identified as key prognostic genes." (PMID 35880088, 2022).